WWTR1 (WW domain containing transcription regulator 1)
Description:
Transcriptional coactivator which acts as a downstream regulatory target in the Hippo signaling pathway that plays a pivotal role in organ size control and tumor suppression by restricting proliferation and promoting apoptosis. The core of this pathway is composed of a kinase cascade wherein STK3/MST2 and STK4/MST1, in complex with its regulatory protein SAV1, phosphorylates and activates LATS1/2 in complex with its regulatory protein MOB1, which in turn phosphorylates and inactivates YAP1 oncoprotein and WWTR1/TAZ. WWTR1 enhances PAX8 and NKX2-1/TTF1-dependent gene activation. In conjunction with YAP1, involved in the regulation of TGFB1-dependent SMAD2 and SMAD3 nuclear accumulation. Plays a key role in coupling SMADs to the transcriptional machinery such as the mediator complex. Regulates embryonic stem-cell self-renewal, promotes cell proliferation and epithelial-mesenchymal transition.
Synonyms: TAZ; DKFZp586I1419
Tractability: Small molecule: a structure with a bound ligand is known. Antibody: UniProt places it where antibodies can reach, with high confidence; its Gene Ontology location is reachable by antibodies, with medium confidence. PROTAC: UniProt records ubiquitination sites on it; ubiquitination databases record sites on it.
Gene: Protein-coding gene on chromosome 3 (149,517,235 to 149,736,714, reverse strand). Ensembl gene ENSG00000018408.
Subcellular location: Nucleus; Cytoplasm; Cell membrane; Cell junction, tight junction
Subcellular location (Human Protein Atlas): Nuclear bodies; Nucleoplasm; Cytosol
Pathways (Reactome):
Gene expression (Transcription): RUNX2 regulates osteoblast differentiation; RUNX3 regulates YAP1-mediated transcription; YAP1- and WWTR1 (TAZ)-stimulated gene expression
Signal Transduction: Downregulation of SMAD2/3:SMAD4 transcriptional activity; SMAD2/SMAD3:SMAD4 heterotrimer regulates transcription; Signaling by Hippo
Developmental Biology: EGR2 and SOX10-mediated initiation of Schwann cell myelination
Immune System: Regulation of PD-L1(CD274) transcription
Muscle contraction: Physiological factors
Gene Ontology:
Molecular function: protein binding; transcription coactivator activity; transcription coregulator activity; transcription corepressor activity; protein homodimerization activity
Biological process: hippo signaling; negative regulation of canonical Wnt signaling pathway; negative regulation of fat cell differentiation; positive regulation of cell population proliferation; positive regulation of epithelial to mesenchymal transition; positive regulation of osteoblast differentiation; SMAD protein signal transduction; stem cell division; positive regulation of protein localization to nucleus; positive regulation of transcription by RNA polymerase II; regulation of canonical Wnt signaling pathway; regulation of DNA-templated transcription; heart process; negative regulation of DNA-templated transcription; tissue homeostasis
Cellular component: cytoplasm; cytosol; nuclear body; nucleoplasm; nucleus; plasma membrane; bicellular tight junction; transcription regulator complex
Genetic constraint (gnomAD): Loss-of-function variants: 12 observed, 35.91 expected, observed/expected ratio (o/e) 0.33, 90% interval 0.21 to 0.54. The upper end of that interval is the gene's LOEUF score, 0.54, which puts it in group 2 of 6, group 1 being the genes least tolerant of losing a copy. Missense variants: 434 observed, 517.73 expected, observed/expected ratio (o/e) 0.84, 90% interval 0.77 to 0.91. Synonymous variants: 229 observed, 206.12 expected, observed/expected ratio (o/e) 1.11, 90% interval 1 to 1.24.
Cancer hallmarks: proliferative signalling (promotes); angiogenesis (promotes); invasion and metastasis (promotes); genome instability and mutations (suppresses); escaping programmed cell death (promotes); cell replicative immortality (promotes); escaping immune response to cancer (promotes); escaping programmed cell death (suppresses); tumour promoting inflammation; change of cellular energetics
Homologues: Orthologues: chimpanzee WWTR1 (100% identical), macaque WWTR1 (98% identical), dog WWTR1 (96% identical), pig WWTR1 (96% identical), guinea pig WWTR1 (95% identical), rabbit WWTR1 (93% identical), mouse Wwtr1 (91% identical), rat Wwtr1 (91% identical), tropical clawed frog wwtr1 (78% identical), zebrafish wwtr1 (62% identical), Drosophila melanogaster yki (22% identical). Paralogues in human: YAP1 (52% identical).
Diseases named in the same sentence as WWTR1 in open-access papers:
WWTR1 is named in the same sentence as 104 diseases in open-access papers, as found by Europe PMC text mining. Sharing a sentence is not in itself a finding about the gene and the disease. The quoted sentences say what the papers report.
epithelioid hemangioendothelioma (20 papers, 2013 to 2025). A low-grade malignant blood vessel neoplasm. "Beyond that, aberrant Hippo signaling can arise from chromosomal translocations involving YAP1 or WWTR1 (encoding TAZ) as in epithelioid hemangioendothelioma, another fusion gene‐driven soft‐tissue tumor." (PMID 30898787, 2019). "For example, in 2011 a rare vascular sarcoma called epithelioid hemangioendothelioma was found to have a WWTR1/CAMTA1 gene fusion and a specific diagnostic fluorescent in situ hybridisation assay for this translocation was devised." (PMID 24216705, 2013). "Diagnoses included ASPSCR1::TFE3 alveolar soft part sarcoma; WWTR1::CAMTA1 epithelioid hemangioendothelioma; INI-1 deficient epithelioid sarcoma; EWSR1::NR4A3 extra-skeletal myxoid chondrosarcoma; and low-grade ARHGAP23::FER spindle cell malignancy, a novel fusion-driven sarcoma." (PMID 39941809, 2025). "The rare vascular sarcoma epithelioid hemangioendothelioma (EHE) is defined by WWTR1 or YAP1 gene rearrangements that result in functional fusion proteins." (PMID 40819258, 2025). "Epithelioid hemangioendothelioma with WWTR1–CAMTA1 fusion shows neoplastic cells embedded in a myxohyaline stroma." (PMID 38066766, 2023). "WWTR1 is a downstream effector of the Hippo signal transduction pathway, a major player in different types of sarcoma, including ARMS, and in epithelioid hemangioendothelioma, WWTR1-CAMTA1 has been identified as a disease-defining gene fusion." (PMID 36232302, 2022). "Remarkably, gene fusion of WWTR1-CAMTA1 (calmodulin-binding transcription activator 1) happens in virtually all epithelioid hemangioendothelioma." (PMID 27412635, 2016). "In this review, we discussed several key sarcoma subtypes characterized by hallmark fusion proteins—such as Ewing sarcoma with EWSR1–FLI1/ERG, epithelioid hemangioendothelioma with WWTR1–CAMTA1/YAP1–TFE1 fusion—and highlighted their clinical implications as targets for therapy." (PMID 40563544, 2025). "Furthermore, chromosomal translocations that generated fusion proteins containing YAP (YAP-TFE3) and TAZ (WWTR1-CAMTA1) are oncogenic drivers in epithelioid hemangioendothelioma." (PMID 31212916, 2019). "Herein, we present a unique TAZ-driven cancer, epithelioid hemangioendothelioma (EHE), which harbors a WWTR1(TAZ)–CAMTA1 gene fusion in at least 90% of cases." (PMID 35740643, 2022). "Epithelioid hemangioendothelioma (EHE) is a rare, malignant vascular sarcoma characterized in most cases by a WWTR1-CAMTA1 fusion." (PMID 31577358, 2019). "Although TAZ and YAP have been shown to be activated oncoproteins in a number of carcinomas and sarcomas, genetic alterations are rare with the exception of the WWTR1-CAMTA1 and YAP1-TFE3 gene fusions in epithelioid hemangioendothelioma (EHE)." (PMID 30167083, 2018). "The negativity for the WWTR1-CAMTA1 fusion gene, which was positive in more than 90% of the cases of epithelioid hemangioendothelioma, confirmed the hypothesis of angiosarcoma." (PMID 39734979, 2024). "The renal EAS is easily misdiagnosed as epithelioid hemangioendothelioma (EHE), as it could show similar characteristics in immunohistochemical staining, such as being positive for CD31, CD34, and ERG, but the results of Ki-67, WWTR1-CAMTA1, and YAP1-TFE3 might be helpful in differential diagnosis." (PMID 39687884, 2024).
breast cancer (16 papers, 2014 to 2024). A primary or metastatic malignant neoplasm involving the breast. "WWTR1 is overexpressed in multiple types of solid tumors and its expression is associated with metastasis of breast cancer, lung cancer and melanoma." (PMID 30976198, 2019). "WWTR1 was previously implicated in breast cancer metastasis and drug resistance." (PMID 27792127, 2016). "A positive correlation of expression of YAP and WWTR1 with expression of HIF1A was detected in breast cancer patients, with particularly high expression of all three genes in basal-like tumors." (PMID 36077517, 2022). "WWTR1 also plays a significant role in migration, invasion and carcinogenesis of breast cancer cells." (PMID 33167967, 2020). "In breast cancer, WWTR1 (also called transcriptional co-activator with PDZ-binding motif) expression is activated by HIF-1α and is important for the maintenance of breast cancer stem cells." (PMID 33121134, 2020). "Our previous studies have shown that geranylgeranylation plays a key role in activation of the YAP/WWTR1 transcriptional co-activator activity in breast cancer cells and migration and invasion of gastric cancer cells." (PMID 30976198, 2019). "Overexpression of WWTR1 has been observed in multiple types of solid tumors, including breast cancer, lung cancer, gastric cancer, colon cancer, renal cancer, liver cancer, ovarian cancer, pancreatic cancer, prostate cancer, melanoma, glioma, and sarcoma." (PMID 30976198, 2019). "Furthermore, we investigated the relationship between the sum of YAP1 and WWTR1 expression and survival in breast cancer patients with different intrinsic subtypes." (PMID 38164185, 2024). "Similarly, breast cancer patients with elevated WWTR1 expression also exhibit poorer outcomes." (PMID 33061801, 2020). "In a previous study, we demonstrated that under hypoxic conditions, HIF-1 increased transcription of the WWTR1 gene encoding TAZ and the SIAH1 gene encoding a ubiquitin ligase that triggers degradation of LATS2, a negative regulator of TAZ nuclear localization in breast cancer cells." (PMID 26059435, 2015). "Accordingly, by exploring RNA-Seq data from breast cancer patients, we show that expression of YAP and especially WWTR1 was increased in TNBC tumors as compared to ER positive tumors." (PMID 36077517, 2022). "Our previous studies have shown that WWTR1 has a role in breast cancer cell migration and invasion, and demonstrated that CYR61, a WWTR1 target gene product, is a prognostic biomarker of GCA, and expression of CYR61 is associated with metastasis of GCA." (PMID 30976198, 2019). "A γRV shuttle vector approach identified previously known (WWTR1, RIN1) and also novel (SHARPIN) breast cancer metastasis genes." (PMID 27792127, 2016). "Four genes WWTR1, RIN1, MAF1 and SHARPIN were identified having significant expression levels in breast cancer patients by meta-analysis." (PMID 27792127, 2016). "SRF, YAP, TAZ (WWTR1) and IL6 are consistently upregulated in BLBC, normal-like breast cancer and claudin-low subtypes." (PMID 26671411, 2015). "In addition, MES TFs, SMAD3, SOX9, WWTR1, and IFI16 had 32, 23, 6, and 5 connections, respectively, and KEGG gene enrichment analysis revealed enrichment for ‘breast cancer’, ‘prostate cancer’, and ‘hepatocellular carcinoma’ processes in addition to ‘miRNA in cancer’ terms." (PMID 35201514, 2021).
lung carcinoma (9 papers, 2019 to 2025). "WWTR1 can promote the progression of lung cancer, and WWTR1 overexpression is closely associated with poor differentiation, poor prognosis and metastasis of non-small cell lung cancer." (PMID 35885905, 2022). "Yes-associated protein 1 (YAP) and WW domain-containing transcription regulator 1 (TAZ) are key components of the Hippo pathway which is commonly deregulated in lung cancer and whose activation determines the upregulation of PD-L1 expression." (PMID 33114576, 2020). "The study showed that activation of YAP1/WWTR1/LEPR dependent transcription is a potent factor of osimertinib resistance in EGFR mutant lung cancer." (PMID 40428391, 2025). "In vitro as well as in vivo studies confirmed that YAP1/WWTR1/TEAD-dependent transcription is acutely activated after osimertinib treatment in EGFR-mutant lung cancer, and pharmacological and genetic ablation of this complex strongly inhibits persister cells." (PMID 40428391, 2025). "We confirmed both in vitro and in vivo that YAP1/WWTR1/TEAD-dependent transcription is acutely activated following osimertinib treatment in EGFR mutant lung cancer and pharmacologic and genetic ablation of this complex strongly suppresses persister cells." (PMID 38658677, 2024). "Analysis of mRNA levels from the CCLE database showed that the expressions of YAP (YAP1) and TAZ (WWTR1) were upregulated in KRAS-mutant lung cancer cells, compared to KRAS wild-type tumor cells." (PMID 34073318, 2021). "Numerous studies have shown that WWTR1 promotes tumor initiation, growth, invasion and metastasis in breast and lung cancers." (PMID 30976198, 2019). "We quantified nuclear YAP1 and WWTR1 IHC expression in the panel of EGFR mutant lung cancer PDX." (PMID 38658677, 2024). "In addition, the knockout of WWTR1 in mice can reduce lung cancer metastasis." (PMID 35885905, 2022). "We show that YAP1/WWTR1/TEAD-dependent transcription is acutely activated following treatment of EGFR mutant lung cancer cells with EGFR inhibitors and that prevention of YAP1/WWTR1 activation strongly suppresses cancer cell persistence." (PMID 38658677, 2024). "Of note, in the two PDX models we tested only one demonstrated YAP1/WWTR1/TEAD-dependent transcription in persister cells, highlighting that other mechanisms of persistence in EGFR mutant lung cancer must exist and need to be defined." (PMID 38658677, 2024). "WWTR1 silencing attenuated CSE1L-promoted colony formation, motility, and invasiveness of human lung cancer and glioblastoma cells." (PMID 34022224, 2021). "Yes Associated Protein 1 (YAP1) and WW Domain Containing Transcription Regulator 1 (WWTR1/TAZ) are key regulatory factors of Hippo Signaling pathways, and are targeted to develop effective lung cancer therapy by their inhibition." (PMID 31641374, 2019).
sarcoma (8 papers, 2016 to 2025). A usually aggressive malignant neoplasm of the soft tissue or bone. "This observational, retrospective effort across Europe, US, Australia, and Asia aimed to assess the activity of systemic therapies in EHE, an ultra‐rare sarcoma, marked by WWTR1‐CAMTA1 or YAP1‐TFE3 fusions." (PMID 33713582, 2021). "The observation that the WWTR1-CAMTA1 and YAP1-TFE3 gene fusions occur in a sarcoma suggests these cancers are particularly susceptible to perturbations within the Hippo pathway." (PMID 27129148, 2016). "Grouping of all 264 sarcomas together including various histological types of sarcoma did not demonstrate a correlation between WWTR1 and YAP1 expression and overall survival (data not shown)." (PMID 27129148, 2016).
glioma (6 papers, 2016 to 2025). A benign or malignant brain and spinal cord tumor that arises from glial cells (astrocytes, oligodendrocytes, ependymal cells). "Subsequently, ROC curve analysis suggested that the AUC values of WWTR1, STEAP3, SLC39A14, NOTCH2, IREB2, HIF1A, and FANCD2 were all 1.000, indicating their potential as diagnostic biomarkers for gliomas." (PMID 37978473, 2023). "In conclusion, we identify seven ferroptosis-associated genes (SLC39A14, WWTR1, STEAP3, NOTCH2, IREB2, HIF1A, and FANCD2) in gliomas, all of which are highly expressed." (PMID 37978473, 2023). "Numerous signaling pathways have been studied in gliomas including Hippo pathway and in particular, its effectors YAP/TAZ, encoded by the gene WWTR1." (PMID 34948224, 2021). "In a continued effort to identify genes that are specifically associated with the survival of IDH-mutant gliomas, we examined IGFBP2, WWTR1, and YAP1, which are associated with glioma progression." (PMID 27852048, 2017). "In addition, several studies have shown that WWTR1 is overexpressed in gliomas and promotes tumor progression through multiple pathways." (PMID 37978473, 2023). "Cross-referencing this list with our in-house RNA-Seq dataset shows several HDACi resistance genes that are expressed at higher baseline levels in our IDHwt glioma cells, including EMP1, WWTR1, EGFR, and AGRN." (PMID 41066183, 2025). "Seven ferroptosis-related hub genes, namely SLC39A14, WWTR1, STEAP3, NOTCH2, IREB2, HIF1A, and FANCD2, were identified, all of which were highly expressed in glioma." (PMID 37978473, 2023). "Among the most prominent TFs involved in glioma EMT are ZEB1, TWIST1, SNAI1/2, TAZ/WWTR1 and the so-called “master regulators“ C/EBPβ and STAT3." (PMID 32178267, 2020). "As expected, IDH-mutant gliomas manifested increased methylation concomitant with decreased expression of IGFBP2, YAP1, and WWTR1 in comparison with IDH-wildtype." (PMID 27852048, 2017). "Furthermore, FZD7 directly regulated the expression of transcriptional coactivator with PDZ-binding motif (TAZ) (also known as WW domain containing transcription regulator 1, WWTR1) in glioma cells, suggesting that FZD7 may promote glioma cell proliferation via upregulation of TAZ." (PMID 27852064, 2016).
hepatocellular carcinoma (6 papers, 2021 to 2025). A malignant tumor that arises from hepatocytes. "In contrast, YAP1 and WWTR1 gene fusions have so far been undetected in some common tumors with prevalent YAP and TAZ activation, such as hepatocellular carcinoma." (PMID 40491864, 2024). "In the cancer cell literature, only two publications have reported contradictory effects of the WWTR1/TAZ paralog, YAP, which represses GDF15 expression in breast cancer and induces expression in hepatocellular carcinoma." (PMID 38201456, 2023). "Transcription factors, yes-associated protein (YAP) and WW domain-containing transcription regulator protein 1 (WWTR1, also known as TAZ) have emerged as critical regulators in human hepatocellular carcinoma (HCC) and cholangiocarcinoma (CC), the two major types of primary liver cancer." (PMID 35439973, 2022).
melanoma (6 papers, 2018 to 2025). A malignant, usually aggressive tumor composed of atypical, neoplastic melanocytes. "For P1, clusters enriched in ER lumen-associated proteins (CIP2A, OSMR, WWTR1), inflammasome-related proteins, and melanoma-specific proteins (CCND1, MITF, MLANA, NOTCH1) were notable." (PMID 40669378, 2025). "This dataset reflects gene dependency in drug-naïve, basal culture conditions and we identified five (out of 62) melanoma cell lines with a predicted dependency on WWTR1/TAZ." (PMID 41193428, 2025).
vascular tumors (6 papers, 2024 to 2025). "Additionally, gene fusions involving FOS, FOSB, YAP1, and WWTR1 have been discovered in vascular tumors, improving diagnostic accuracy." (PMID 40428263, 2025). "The WWTR1::CAMTA1 fusion gene can induce endothelial cells to transform into vascular tumors with EHE characteristics." (PMID 40040722, 2025). "When unable to be clearly differentiated from other vascular tumors, the presence of the WWTR1-CAMTA1 translocation can aid the diagnosis of EHE." (PMID 39196615, 2024). "Fusion transcripts involving the FOSB gene on 19q13 with SERPINE1 (7q22), ACTB (7p22) and WWTR1 (3q25) have been detected and may be useful in the differentiation of PMH from other vascular tumors." (PMID 40277775, 2025).